CCNE1 (cyclin E1)
Diseases named in the same sentence as CCNE1 in open-access papers (continued):
Sharing a sentence is not in itself a finding about the gene and the disease.
endometrioid tumor (3 papers, 2018 to 2025). A benign, borderline, or malignant epithelial tumor of the female reproductive system characterized by the presence of glands and/or cysts lined by neoplastic cells that resemble endometrial cells. "CCNE1 amplification appears to be the primary biomarker associated with non-endometrioid tumors in populations of African descent." (PMID 41257933, 2025). "Our study provides insight into the current molecular classification by linking CCNE1 amplification to non-endometrioid tumors." (PMID 41257933, 2025). "Notably, our latest results validate our initial findings, with 66% of non-endometrioid subtypes harboring CCNE1 amplification compared to 8% of endometrioid tumors, demonstrating a strong association between CCNE1 amplification and non-endometrioid subtypes (p < 0.0001)." (PMID 41257933, 2025).
head and neck squamous cell carcinoma (3 papers, 2020 to 2025). A squamous cell carcinoma that arises from any of the following anatomic sites: lip and oral cavity, nasal cavity, paranasal sinuses, pharynx, larynx, and salivary glands. "For example, FBW7, an E3 ubiquitin ligase, interacts with SNX5 to reduce the ubiquitination and degradation of cancer-associated proteins such as c-Myc, NOTCH1, and Cyclin E1, thereby promoting the progression of head and neck squamous cell carcinoma (HNSCC)." (PMID 40144551, 2025). "In head and neck squamous cell carcinoma (HNSCC) SNX5 interacts with the E3 ligase F box proteins, thereby blocking FBW7 mediated ubiquitination of oncoproteins including c-Myc, NOTCH, and cyclin E1." (PMID 33374212, 2020).
Lymph Node Metastasis (3 papers, 2022 to 2025). "However, only the expression levels of the proliferation-related genes Cyclin D1 and Cyclin E1 were significantly associated with the lymph node metastasis, and only the Cyclin E1 and MMP9 expression levels showed significant correlation with distant metastasis (M stage)." (PMID 34975298, 2022).
metastasis (3 papers, 2021 to 2025). The spread or migration of cancer cells from one part of the body (where they first appeared) to another. "While CCNE1 amplification has been reported to be associated with liver metastasis, MGPT data from C-CAT suggested that CCNE1 amplification might play an important role for not only liver metastasis but also LN metastasis in GC." (PMID 40565509, 2025). "Similarly, patients with a positive status of CCNE1 demonstrated higher ratio of lymphovascular invasion (P = 0.012) and liver metastasis (P = 0.003)." (PMID 34168152, 2021).
nasopharyngeal carcinoma (3 papers, 2014 to 2019). A carcinoma arising from the nasopharyngeal epithelium. "Overexpression of miR-188 inhibits cell proliferation, tumor colony formation and G1/S cell cycle transition in human nasopharyngeal carcinoma CNE cells by inhibiting CCND1, CCND3, CCNE1, CCNA2, CDK4 and CDK243." (PMID 27708404, 2016). "In previous studies, miR-26a/b have been shown to block the G1/S transition of the cell cycle by targeting CCND2, CCNE1/2, CDK6, and EZH2 in HCC and nasopharyngeal carcinoma, and to restrain metastasis by suppressing the expression of IL6 in HCC." (PMID 24565101, 2014).
Obesity (3 papers, 2022 to 2023). Accumulation of substantial excess body fat.
small cell lung carcinoma (3 papers, 2015 to 2021). Small cell lung cancer (SCLC) is a highly aggressive malignant neoplasm, accounting for 10-15% of lung cancer cases, characterized byrapid growth, and early metastasis. "It's worth noting that E2F1 and CCNE1 had high MCODE score in DMDD targets PPI and both of them were demonstrated to be associated with cell cycle and pathways in cancer and small cell lung cancer." (PMID 33613291, 2021).
uterine tumors (3 papers, 2022 to 2024).
adenoma (2 papers, 2021). A neoplasm arising from the epithelium.
alveolar rhabdomyosarcoma (2 papers, 2022 to 2024). A rapidly growing malignant mesenchymal neoplasm. "We did not observe a similar increase in adavosertib IC50 dose or CCNE2 mRNA expression in A673 (ES, EWSR1-FLI1+) and RH41 (alveolar rhabdomyosarcoma, PAX3-FOXO1+) cells upon CCNE1 KD." (PMID 35315355, 2022).
astrocytoma (2 papers, 2017 to 2022). "NUSAP1 also upregulated the expression of the downstream targets of HH pathway including PTCH1, HIP1, CCND1, CCNE1 and HDAC1 in astrocytoma." (PMID 28899410, 2017).
atherosclerosis (2 papers, 2016 to 2024). A disease characterized by the build-up of fatty material and calcium deposition in the arterial wall resulting in partial or complete occlusion of the arterial lumen. "In this study, we demonstrated that Kiom-18, a novel composition of C. cassia, P. densiflora, C. longa and G. glabra, prevents atherosclerosis through the anti-proliferative effect on VSMCs via the regulation of cell cycle-related proteins such as CDK2, CDK4, cyclin D1, cyclin E1, Rb, and PCNA." (PMID 27465365, 2016).
chordoma (2 papers, 2020 to 2022). Chordomas are rare malignant tumors arising from embryonic remnants of the notochord in axial skeleton. "By survival analysis, high cyclin E1 expression was an independent prognostic risk factor for chordoma patients along with advanced disease status and positive surgical margin." (PMID 33282745, 2020). "Overall, cyclin E1 overexpression was an independent prognostic risk factor for poor chordoma patient outcomes." (PMID 33282745, 2020). "While we have identified a significant correlation between cyclin E1 expression and chordoma patient prognosis, future works should focus on the mechanism of the overexpression of cyclin E1 in chordoma and how cyclin E1 overexpression causes chordoma cell proliferation and poor outcomes." (PMID 33282745, 2020). "In total, our work supports cyclin E1 as a diagnostic biomarker in chordoma." (PMID 33282745, 2020). "Additionally, the presence of a CCNE1 deletion occurred exclusively in cluster 2 (8/10) chordomas and low-risk-group (6/10) chordomas, whereas all RB1 and CDKN2A/2B deletions occurred in cluster 1 and RB1 (5/6) deletions and CDKN2A/2B (2/3) deletions patients who were in the high-risk group." (PMID 36439461, 2022). "Sixty-three percent of the chordoma patient specimens in the TMA, fifty-six percent of the fresh chordoma tissues, and all chordoma cell lines showed high cyclin E1 expression." (PMID 33282745, 2020). "In chordoma cell lines, Western blots showed cyclin E1 was expressed in both UCH2 and CH22, with CH22 having notably high expression." (PMID 33282745, 2020). "In summary, we show cyclin E1 is overexpressed in most chordomas, and its expression positively correlates to disease status and inversely correlates with OS, RFS, and MFS of chordoma patients." (PMID 33282745, 2020). "All chordoma tissue samples showed cyclin E1 expression, including five with high expression (55.6%) and 4 with low expression (44.4%)." (PMID 33282745, 2020). "Essentially, a more advanced chordoma staging correlated to higher cyclin E1 expression (advanced versus primary, 2.1 ± 1.0 versus 1.4 ± 0.9, P=0.002)." (PMID 33282745, 2020). "Our TMA analysis showed cyclin E1 expression positively correlates with chordoma patient disease status." (PMID 33282745, 2020). "In our study, overexpression of cyclin E1 occurred in 62.7% of chordoma patients, and is consistent with findings in more common cancers." (PMID 33282745, 2020). "Our work suggests cyclin E1 as a prognostic biomarker for chordoma patients and supports future works investigating its mechanism and pathway as a potential drug target." (PMID 33282745, 2020). "We further evaluated cyclin E1 expression in nine fresh chordoma tissues and two chordoma cell lines." (PMID 33282745, 2020). "Seventy-five chordoma patient specimens were enrolled in a tissue microarray (TMA) to evaluate cyclin E1 expression via immunohistochemical staining." (PMID 33282745, 2020). "In response, we sought to investigate the expression of cyclin E1 in chordoma and its correlation, if any, to clinicopathologic features or prognosis within chordoma patients." (PMID 33282745, 2020). "Because recurrence and subsequent metastasis are of particular significance in determining chordoma outcomes, the ability of cyclin E1 overexpression to function as a prognostic biomarker is especially noteworthy for correlating with RFS and MFS in our study." (PMID 33282745, 2020). "Taken together, cyclin E1 expression is a promising prognostic biomarker for chordoma patients that may help guide clinical decision making." (PMID 33282745, 2020). "In response, because cyclin E1 overexpression correlates with patient prognosis in several malignancies, we investigated its expression in chordoma and whether it informs patient prognosis." (PMID 33282745, 2020). "Western blot was used to assess cyclin E1 expression in chordoma cell lines and fresh tissues." (PMID 33282745, 2020).
chordoma (continued). "It therefore follows and is clear that cyclin E1 overexpression advances chordoma." (PMID 33282745, 2020). "Third, the mechanisms of cyclin E1 overexpression in chordoma remains unknown and need be further investigated." (PMID 33282745, 2020). "Despite these established findings in other cancers, the expression and clinical significance of cyclin E1 in chordoma is unknown." (PMID 33282745, 2020). "Future investigations to validate and build on the prognostic value of Cyclin E1 in chordoma will be carried out on a larger sample size collaborating with neurosurgeons to include skull base chordoma, and will focus on the detail mechanism and regulation of cyclin E1 expression in chordoma." (PMID 33282745, 2020). "However, future studies to increase the number of specimens are needed to validate cyclin E1 as a biomarker for chordoma prognosis." (PMID 33282745, 2020). "Moreover, while molecular targeting therapies have been investigated in chordoma but have largely been underwhelming, the cyclin E1 should be investigated as a novel therapeutic strategy for chordoma patients." (PMID 33282745, 2020). "In TMA analysis, cyclin E1 expression positively correlated to chordoma patient disease status." (PMID 33282745, 2020). "Cyclin E1 is a promising biomarker predicting chordoma patient prognosis." (PMID 33282745, 2020). "We then correlated cyclin E1 staining intensity in the TMA to clinicopathological features and chordoma patient outcomes." (PMID 33282745, 2020). "In our study, cyclin E1 showed prognostic significance with respect to OS, RFS and MFS in chordoma patients." (PMID 33282745, 2020). "Additionally, the presence of a CCNE1 deletion was exclusively found in the group of chordoma patients with better outcome, whereas RB1 and CDKN2A/2B deletions were mainly found in the group of chordoma patients with worse outcome." (PMID 36439461, 2022).
COVID-19 (2 papers, 2022 to 2023). A disease caused by infection with severe acute respiratory syndrome coronavirus 2. "The network pharmacology analysis identified seven core targets (namely, AURKA, CDK1, CCNB1, CCNB2, CCNE1, CCNE2, and TTK) of curcumol in patients with COVID-19 and LUAD." (PMID 35520289, 2022). "The molecular network analysis using Cytoscape highlighted seven core targets of curcumol, namely, AURKA, CDK1, CCNB1, CCNB2, CCNE1, CCNE2, and TTK in COVID-19 and LUAD." (PMID 35520289, 2022). "We identified seven core pharmacological targets of curcumol, namely, AURKA, CDK1, CCNB1, CCNB2, CCNE1, CCNE2, and TTK, in treating LUAD and COVID-19." (PMID 35520289, 2022).
diabetes (2 papers, 2019 to 2023). "In ECs, MiR-503 directly downregulates CCNE1 and cdc25A in a situation mimicking ischemia and diabetes (high glucose/low growth factors)." (PMID 31035988, 2019). "Furthermore, the PPN-delivered miR-503 inhibitor effectively modulates endothelial cell expression of miR-503 and its downstream targets, CCNE1 and CDC25a, thereby enhancing endothelial angiogenesis in diabetes-like conditions as demonstrated by tubulogenesis and migration in vitro." (PMID 37630945, 2023).
endometrioid carcinomas (2 papers, 2017 to 2022). "We observed 19q12 (CCNE1/URI) amplification in 10% of the entire EC group, most frequently in advanced stage non-endometrioid and high-grade endometrioid carcinomas (type II)." (PMID 27582547, 2017).
Fanconi anemia (2 papers, 2023 to 2025). Fanconi anemia (FA) is a hereditary DNA repair disorder characterized by progressive pancytopenia with bone marrow failure, variable congenital malformations and predisposition to develop hematological or solid tumors. "Co-occurrence of CCNE1 amplification with RB1 loss and somatic mutations in genes involved in HR, Fanconi anemia (FA), and DNA repair was assessed using patient data from The Cancer Genome Atlas (TCGA)." (PMID 37519629, 2023).
HCMV infection (2 papers, 2010 to 2014). "Whereas Cyclin D1 expression was largely unaffected by HCMV infection and all four viruses led to a strong and sustained induction of Cyclin E1, they markedly differed with respect to Cyclin A2, Cyclin B1 and APC5 protein regulation." (PMID 25393019, 2014). "Furthermore, as is the case with cyclin E1, cyclin E2 levels were induced by HCMV infection in all serum conditions." (PMID 20585629, 2010).
infertile (2 papers, 2014 to 2021). "Further, loss of one Ccne1 allele in the absence of cyclin E2 results in infertility as does loss of the remaining Ccne1 allele, but with even more severe meiotic abnormalities." (PMID 24586195, 2014).
iron deficiency (2 papers, 2019 to 2024). "Additionally, iron deficiency can inhibit cyclin E1 induction and S-phase entry after B-cell activation leading to low IgG and IgM production in iron-deficience mice." (PMID 39127747, 2024). "We show that iron is essential for B cell proliferation; both iron deficiency and α-ketoglutarate inhibition could suppress cyclin E1 induction and S phase entry of B cells upon activation." (PMID 31270335, 2019).
male infertility (2 papers, 2010 to 2024). The inability of the male to effect fertilization of an ovum after a specified period of unprotected intercourse. "In addition, cyclin E1+/- E2-/- mice display more pronounced testicular hypoplasia and male infertility than cyclin E2-/- mice, indicating that it is unlikely that excess cyclin E1 causes this phenotype, as the phenotype is more severe when a cyclin E1 allele is removed." (PMID 20180967, 2010). "Deletion of FBXW7 in germ cells suppresses differentiation by upregulation of MYC and CCNE1 and leads to male infertility, which is similar to the phenotype of Cwf19l2‐SKO mice in this study." (PMID 38889293, 2024). "Of interest, cyclin E2, but not cyclin E1, is upregulated by the p110 isoform of the transcription factor CDP/Cux and CDP/Cux knockout mice also suffer from male infertility, although without testicular atrophy." (PMID 20180967, 2010).
metastatic cancer (2 papers, 2024 to 2025). A carcinoma which has spread from the original site of growth to another anatomic site. "CCNE1 amplification has been found to be associated with worse prognosis in a variety of metastatic cancers, including PDAC." (PMID 39941707, 2025).
renal cell carcinoma (2 papers, 2019 to 2022). "Silencing of tumor susceptibility 101 reduced proliferation and induced G0/G1 arrest by markedly decreasing the expression of cyclin E1/CDK2 in renal cell carcinoma." (PMID 35246013, 2022).
serous ovarian tumors (2 papers, 2017). "CCNE1 amplification, occurring in ∼20% of the high grade serous ovarian tumors, was previously proposed as a marker for platinum resistance and poor prognosis as well as for CDK2 inhibition." (PMID 28977941, 2017).
viral infections (2 papers, 2018 to 2022). "Other members of the network also reappeared in the gene set enrichment analysis as members of pathways associated with viral infections (DDX58, IFIT1, IRF1, MX1, STAT1) or viral carcinogenesis and cell cycle (CCND1, CCND3, CCNE1, CDC20, E2F2, RANBP1)." (PMID 30042828, 2018).
Acute hepatitis (1 paper, 2021). Acute hepatic injury resulting from inflammation typically accompanied by increased serum alanine transaminase activity. "In line with this hypothesis, we have recently shown that systemic knockdown of Ccne1 in mice with acute hepatitis resulted in reduced cell cycle activity of myeloid cells, and CCNE1 signalling was shown to be involved during myeloid development." (PMID 34830835, 2021).
Alzheimer disease (1 paper, 2020). A progressive, neurodegenerative disease characterized by loss of function and death of nerve cells in several areas of the brain leading to loss of cognitive function such as memory and language. "Interestingly, cell cycle dysregulation was recently identified in single cell RNA-seq analysis of microglia from a mouse model of Alzheimer’s disease (AD), with some of the same genes identified in our study, including Top2a, Hells, Ccne1, Spc25, Cenpe, Anln, Rsad2, and Ifitm335." (PMID 32792571, 2020).
Amoebiasis (1 paper, 2024).
anaplastic large cell lymphoma (1 paper, 2022). Anaplastic large cell lymphoma (ALCL) is a rare and aggressive peripheral T-cell non-Hodgkin lymphoma, belonging to the group of CD30-positive lymphoproliferative disorders, which affects lymph nodes and extranodal sites. "In addition, Hoareau-Aveilla C. and colleagues studied its role in NPM-Anaplastic large cell lymphoma (NPM -ALK+ ALCL) cells, where it regulates the expression of cyclin E1, CDK6, and E2F3." (PMID 36498861, 2022).
Burkitt lymphoma (1 paper, 2017). A rare form of malignant mature B-cell non-Hodgkin lymphoma. "Remarkably, miR-103 inhibits CDK2 and cyclin E1 in ALL and Burkitt's lymphoma cells as in the mouse intestinal crypt." (PMID 27888798, 2017).
carcinoids (1 paper, 2015). "ASCL1 (p = 0.0016), BCL2 (p < 0.0001), CASP8 (p = 0.0030), CCNE1 (p = 0.0135), CDK1 (p = 0.0146), CDK2 (p = 0.0114), CDKN1A (p = 0.0107) and CDKN2A (p = 0.0002) showed lower expression in carcinoids compared to carcinomas." (PMID 26008974, 2015). "In contrast, CCNE1 and CDK6 showed elevated expression in carcinoids compared to carcinomas." (PMID 26008974, 2015).